S100A8 (S100 calcium binding protein A8)
Diseases named in the same sentence as S100A8 in open-access papers (continued):
Sharing a sentence is not in itself a finding about the gene and the disease.
infection (continued). "However, elevated, and persistent production of S100A8/9 can cause severe damage to heart tissue during infection." (PMID 37624851, 2023). "A very intriguing finding was reported recently that the S100A8/A9 tetrameric complex calprotectin is released from neutrophils as the NETs associated protein in response to infection, representing a novel unrecognized route of calprotectin extracellular release." (PMID 22489132, 2012). "The role of S100A8/A9 during a local infection of the urinary tract system caused by E. coli remains unknown." (PMID 20976233, 2010). "Therefore, systemic and long-term suppression of S100A8/S100A9 may increase susceptibility to infections." (PMID 41476978, 2025). "Based on the wide and varied roles of S100A8/A9, expression and secretion can change during inflammation and may vary widely in differing causes of inflammation, such as that caused by composite trauma versus infection or cancer." (PMID 35874126, 2022). "However, calprotectin is also known to have an anti-inflammatory or protective role during infection and inflammation and there is an ongoing controversy on whether S100A8/A9 is pathogenic or rather protective." (PMID 32107497, 2020). "S100a9 normally functions in complex with S100a8 in response to infection by inducing pro-inflammatory cytokines, reactive oxygen species, and nitric oxide." (PMID 39510801, 2025). "The additional results revealed lower S100A8 mRNA and protein expression in both the KD-1 group and the KD-2 group compared with the HT-1376 group and NC group, and the knockdown infection efficiency in the KD-1 group was stronger than that in the KD-2 group." (PMID 39895787, 2025). "In the present study, S100A8 was overexpressed and knocked down by overexpression lentivirus and shRNA lentivirus infection of HT-1376 cells, respectively, and the infection efficiency was verified using WB and RT-qPCR." (PMID 39895787, 2025). "The expression of Mmp8, S100a8 and S100a9 in the mNeu and immNeu of infection groups was predominantly decreased in the blood." (PMID 40874427, 2025). "Using RT-qPCR to quantify proinflammatory MPO, S100a8, as well as iNOS expression in neutrophils, we observed significant upregulation after 6 h of infection with fas2Δ/Δ compared to WT." (PMID 40138332, 2025). "S100A8 is produced predominantly by neutrophils and macrophages and has been extensively studied in various inflammatory diseases, including infection-induced inflammation, metabolic inflammation, immune system dysfunction, and degenerative diseases." (PMID 40962953, 2025). "S100A8/A9 are secreted by myeloid cells such as neutrophils and monocytes upon infection with bacteria." (PMID 39337466, 2024). "Inflammatory processes such as infection, trauma, heat, stress, and others intensively increase levels of S100A8/A9 in those cells." (PMID 38672106, 2024). "S100A8/A9 plays an important role in protecting the body from pathogen infection through multiple inflammatory pathways mediated by TLR4 or RAGE." (PMID 39061526, 2024). "Under conditions such as inflammation and infection, the expression level of S100A8 is typically elevated." (PMID 37554330, 2023). "We also conducted a similar experiment in C57BL/6 mice, where we observed a significant increase in plasma levels of S100a8/a9 on days 2 and 10 post-infection." (PMID 37396347, 2023). "To further validate our findings from RNAseq analysis, we infected mice i.v. with S. aureus Newman WT or Newman ΔsrtA/B and on day 2 after infection, S100a8 and a9 gene expression levels in the blood were compared between the groups." (PMID 37396347, 2023). "Previous studies have demonstrated that ~45% of the neutrophil’s cytoplasmic protein content are S100A8 and S100/A9, that are rapidly released in response to infection, inflammation, and other events of cellular stress." (PMID 37624851, 2023). "disseminated into the heart, indicating S100A8/9 plays a critical role in restricting P.a. to the lungs during infection." (PMID 37624851, 2023).
infection (continued). "Considering that S100A8 can be upregulated during infection and cytokine stimulation in cells other than neutrophils, we measured oxidative burst in various peripheral blood cell types from Mrp8-Cre.TN3 strains before and after pristane injection." (PMID 36853827, 2023). "When released by neutrophils upon infection, S100A8/A9 proteins are capable of binding several metal ions." (PMID 37467233, 2023). "For example, induction of S100A8 expression was nearly equal for all four mycobacteria, while infection percentages between the four strains were variable." (PMID 37822359, 2023). "In cases of severe localized infection, S100A8/A9 is secreted extracellularly to recruit large numbers of immune cells toward the center of infection." (PMID 37180431, 2023). "infection enhances the infiltration of myeloid cells into the lungs, specifically neutrophils, resulting in release of inflammatory cytokines and S100A8/A9." (PMID 37624851, 2023). "Neutrophils or macrophages secret S100A8/A9 to magnify infection-induced inflammation by triggering advanced glycation end products (RAGE) and Toll-like receptor 4 (TLR4) signaling." (PMID 38093319, 2023). "Infection-induced inflammation is one of the primary resources of S100A8/A9 (also known as calprotectin), which is expressed and secreted by immune cells and cells in local lesions." (PMID 36611779, 2023). "During infection, neutrophils are the major source for S100A8/A9, which modulate the inflammatory process via induction of inflammatory cytokines, reactive oxygen species, and nitric oxide." (PMID 37624851, 2023). "During infection, excessive S100a8/a9 expression intensifies the inflammatory response and speeds up the release of cytokines by neutrophils and macrophages, which creates a vicious cycle and worsens the disorder." (PMID 37396347, 2023). "After infection with bacteria, neutrophils, macrophages and monocytes secrete S100A8/A9 to modulate inflammatory processes characterized by the production of cytokines, reactive oxygen species (ROS) and nitric oxide (NO)." (PMID 37420291, 2023). "These two cell types, typically defined by expression of Ly6g (neutrophils) and Adgre1 (F4/80, macrophages), expressed a similar transcriptional program following infection, including S100a8/9, Lcn2, Cxcl1, and Il1b." (PMID 38096412, 2023). "NF-κB–dependent down-regulation of PIRAT during infection enhances PU.1 binding to the S100A8 and A9 promoters." (PMID 35998224, 2022). "The S100A8/A9 dimer stimulates leukocyte recruitment and induces cytokine secretion to regulate the inflammatory response during inflammation infection." (PMID 35928229, 2022). "Intriguingly, although the transcriptional profiles of the caput in sham- and UPEC-infected mice were very similar, upregulation of a few infection-related genes such as S100a8, S100a9, and Slfn4 was indicative for the presence of UPEC in the infected caput." (PMID 36515584, 2022). "reuteri+SL1344 group further confirm that the S100A8/S100A9–NF-κB pathway played an important role in infection of mice induced by S. Typhimurium SL1344." (PMID 35658572, 2022). "With the infection of larval E. granulosus, there were higher expression levels of many inflammatory factors in splenic B cells, such as Cxcl5, Il1r1, S100a8, S100a9, and CD14, which form a complex network of immune regulation." (PMID 35548052, 2022). "Notable abundant genes that also showed highly dynamic expression across the infection course in monocytes include S100A8 and S100A9, which were also up-regulated at Day −2." (PMID 35345453, 2022). "The expression levels of IL8 and S100A8 are shown to be important markers that reflect the infection status of a cow when inflammation is established." (PMID 36139219, 2022). "Treatment of mice with gefitinib inhibited C. albicans-induced phosphorylation of both EphA2 and EGFR in the oral epithelial cells, and reduced the tissue levels of CXCL1/KC, CCL20, and S100A8 after both 1 and 2 days of infection." (PMID 33471869, 2021).
infection (continued). "Infection with NTHi markedly increased the concentrations of defensin-β2, S100A8 and S100A9 in the BAL of both control and CS-exposed mice." (PMID 33784296, 2021). "We found an increased total number of cells in the airways, including neutrophils, DCs, and T cells, as well as enhanced expression of Cxcl1, S100a8, and S100a9 after RV‐A1b infection in Mir146a/b−/‐ mice compared to wt mice." (PMID 34185416, 2021). "Similar findings were observed in Trypanosoma cruzi-infected mice, which displayed an enhanced cardiac expression of S100A8 and S100A9 upon infection in association with an increased presence of MDSC in the heart." (PMID 34065891, 2021). "The validation using Elisa kits found that key proteins Mmp9 and S100a8/a9 were significantly increased in mouse lung tissue during A. baumannii clearance (Infection versus Control, nominal p < 0.05)." (PMID 34025711, 2021). "The cytokine IL-17A has the function of inducing granulopoiesis, inflammatory response, recruiting neutrophils, inducing fungicidal activity, inducing microbial peptides such as S100A7, S100A8, and promotion of resistance to infection." (PMID 33302372, 2020). "During infection, tissue damage, neutrophil extracellular trap formations (NETs), and cellular necrosis, the levels of S100A8 and S100A9 are increasingly expressed in circulating neutrophils and monocytes and can also be secreted passively." (PMID 32107497, 2020). "One possible explanation is that the circumvention of the skin barrier and the lymphatic route leads to the increased worm burden upon intravenous infection in S100A8/A9-/- mice." (PMID 32107497, 2020). "A key way the host restricts the availability of zinc at sites of infection is through the S100A8/S100A9 heterodimer calprotectin, which is produced by a range of host cells but predominantly by neutrophils at infection sites." (PMID 32817386, 2020). "RAW264.7 cells were transfected with an effective short-hairpin RNA1 (shRNA1) against S100A8 and control shRNA2/3, then infected with bacteria for mixed infection assay." (PMID 32457723, 2020). "Any sort of stress and cell damage triggers the release of S100A8/A9 like infections, malignancies, burns, and trauma." (PMID 32425933, 2020). "In another model of murine fungal keratitis, 1 μg of recombinant S100A8/A9 injection into the corneas of S100A9−/− mice restored the ability to inhibit the hyphal growth of Aspergillus fumigatus 24 h post infection." (PMID 32664205, 2020). "As expected, isotype-treated S100A8/A9-/- mice had reduced worm counts compared to WT controls at 12dpi, confirming our previous results upon natural infection." (PMID 32107497, 2020). "Previous reports have identified both high levels of S100A8 and strong neutrophil recruitment in a murine infection model." (PMID 33081210, 2020). "Upon infection, expression of S100A8 increased in both Zn-restricted and Zn-replete mice in the lungs and blood." (PMID 31437249, 2019). "During infection, bacterial effectors can induce S100A8/S100A9 expression, which is released by activated phagocytes." (PMID 31848284, 2019). "In EBOV-infected NHPs, S100A9 was increased 8.43 fold from pre-infection levels by Day 6 PI, and S100A8 levels increased by 4.95 fold." (PMID 30774579, 2019). "The S100A8/A9 complex also protects the host from infection by triggering toll-like receptor 4 (TLR4) and receptor for advanced glycation end-products (RAGE)-mediated inflammatory pathways, and through the recruitment of neutrophils." (PMID 31619666, 2019). "The early expression of S100 proteins during infection-induced inflammation suggests that S100A8 and S100A9 participate in innate immunity and mediate the inflammatory response." (PMID 29942307, 2018). "Nematode infections have previously been reported as the reason behind neutrophil recruitment in response to high S100A8 and S100A9 protein expression levels." (PMID 30245697, 2018).
infection (continued). "Further studies are needed to validate the role of S100A8/A9 as a biomarker to predict infection after trauma and test its utility for antibiotic early prescription." (PMID 29178941, 2017). "High persistent levels of S100A8/A9 have been documented in acute and chronic inflammation, tissue remodeling, and infection." (PMID 29178941, 2017). "S100a8 and S100a9 recruitment results in the elimination of Leishmania and knockout mice experiencing a more severe infection." (PMID 27490109, 2016). "In a murine Salmonella model induced by S. Typhimurium increased levels of endogenous S100A8/A9 complexes were seen both at the primary site of infection and at distant sites corresponding with stage and severity of disease." (PMID 25860480, 2015). "Anti-microbial peptides DefB1 and S100A8 are upregulated in colons of C. difficile-infected mice at distinct time points during infection." (PMID 26230099, 2015). "Previous reports have demonstrated a dual role for S100A8/A9 in severe infection depending on the pathogen it encounters and the stage of disease." (PMID 25860480, 2015). "QRT-PCR confirmed significant induction of RegIIIβ, RegIIIγ, Lcn2, Ltf, S100a8, and S100a9 mRNA levels following infection." (PMID 26658437, 2015). "Concurrently, the expression of S100A8 in the C. difficile challenged mice followed that of the uninfected controls with the exception of a significantly upregulated peak on day 4 post-infection." (PMID 26230099, 2015). "In liver homogenates, S100A8/A9 levels also increased markedly during the course of infection reaching peak values at 5 days post-infection (4535 ng/ml with 105 CFU and 8827 ng/ml with 106 CFU, P = 0.018)." (PMID 25860480, 2015). "S100A8/A9, an extracellular protein complex, is such a danger signal that is able to further amplify the systemic inflammatory response upon infection." (PMID 25860480, 2015). "Calprotectin is a heterodimer composed of S100A8 and S100A9, two members of the large S100 family of calcium-binding proteins implicated in defense against infection." (PMID 24204275, 2013). "Here we show that following HV-68 infection, serum levels of S100A8 or S100A9 increase during acute infection and are maintained during the establishment of viral latency." (PMID 22507226, 2012). "The rationale for the present work stems from our discovery that infection with this gammaherpesvirus resulted in an increase in S100A8/A9 production in vivo, which correlated with an increase in CD11b+Gr-1+ cells." (PMID 22946998, 2012). "Calprotectin consists of the Ca2+-binding proteins S100a8 and S100a9 that are induced in epithelial cells in response to tissue damage and infection." (PMID 23241281, 2012). "It should be noted that the results shown here represent serum levels of S100A8/A9 and numbers of CD11b+Gr-1+ cells at an experimental endpoint (i.e. 44 days post 4 T1 transplantation and 226 days post-HV-68 infection)." (PMID 22946998, 2012). "Recently, the contribution of S100A8/A9 protein complex during infection has been appreciate again due to its pro-inflammatory properties and interaction with TLR4." (PMID 20976233, 2010). "So far, the knowledge about the contribution of S100A8/A9 during (urinary tract) infection is limited." (PMID 20976233, 2010). "Furthermore, the infection sensitizes epithelial cells by upregulating the expression of Toll-like receptor 4, a key receptor that mediates S100A8/A9 signaling." (PMID 41853711, 2026). "To assess the impact of the route of infection on inflammatory signaling, we measured the production of the neutrophil recruitment chemokine, KC protein, and the proinflammatory neutrophil marker S100A8/A9, also known as calprotectin, in brain tissue homogenates." (PMID 39612479, 2025). "In contrast, we detect increased release of S100A8 in the same condition suggesting that STM may also regulate calprotectin during infection." (PMID 39565098, 2024).
infection (continued). "Therefore, we crossed Btkfl/fl with S100a8-Cretg mice and found that S100a8-Cre/Btkfl/fl mice exhibited significantly greater mortality after infection (62% mortality versus 27% in littermate control mice)." (PMID 38696257, 2024). "In both infection scenarios, S100a8-supplemented MN mice showed less intestinal and also less systemic inflammation as measured by restricted increases of Lcn-2 levels in the stool and blood upon infection compared to untreated MN pups." (PMID 39366940, 2024). "Subsequently we have also demonstrated that ▵vapC12 promoted the influx of pro-inflammatory myeloid cells at the site of infection resulting in robust transcription of S100A8/A9 proteins providing enhanced growth benefit to the mutant strain as compared to the WT." (PMID 38515752, 2024). "The correlation between bioluminescent signals from whole mice or kidneys and various clinical parameters—including weight loss, kidney abscess scores, kidney CFU counts, as well as blood levels of S100A8/A9 and IL-6 analyzed on day 10 post-infection in both NMRI and C57BL/6 mice." (PMID 39204252, 2024). "By contrast, DCCs upregulated genes such as Lcn254, whose product binds bacterial siderophores to thwart iron sequestration from the host, and S100a8/955 (calprotectin), a calcium/zinc-binding metal chelator that prevents bacterial uptake of metal ions during Cr infection." (PMID 38600382, 2024). "Likewise, in both infection settings, LI shortening as well as infection-induced influxes of PMNs into the LI mucosa were significantly reduced following S100a8 supplementation." (PMID 39366940, 2024). "Additionally, we examined the plasma protein levels of S100a8/a9 on day 2 after infection in those groups." (PMID 37396347, 2023). "It is well known that S100A8/A9 plays an important role in defense against pathogen infection." (PMID 38093319, 2023). "Though S100A8/A9 plays a critical role in the immune response at sites of infection, our data revealed that S100A8/A9 deficiency did not impact the number of BAL cells and CD45+ cells in the BALF." (PMID 37624851, 2023). "Again, the contradictory results regarding the role of S100A8/A9 in lowering divalent metal ions may be related to the different pathogenicity profiles of the pneumococcal strains and thereof developing infection phenotypes employed." (PMID 37467233, 2023). "For example, immunological signatures are altered during severe infection, and levels of a wide range of pro-inflammatory cytokines [such as S100A8/A9, interleukin 1 beta, interleukin 6 (IL-6), IL-8, CXCL10, and tumor necrosis factor alpha (TNFα)] are dramatically increased." (PMID 37936693, 2023). "Furthermore, Cxcl3 (FC = 41.4) and the antimicrobial proteins S100a9, S100a8 (FC = 204.3 and 90.7), and Ccl3l1 (FC = 28.5) were strongly upregulated by infection." (PMID 38251349, 2023). "infection and the role of S100A8/A9 in the regulation of heart function during infection." (PMID 37624851, 2023). "In addition, documented to recruitment neutrophil during inflammation, S100A8 mRNA expression was reduced in lungs of IL-21R−/− mice after infection, which also partly accounted for lower neutrophil chemotaxis when IL-21/IL-21R blocked." (PMID 35693111, 2022). "In our study, S100A8 increased correlated with leukocyte infiltrations in the early phase of infection, especially in α-GalCer-stimulated mice; although exact mechanisms against vaginal C. albicans infection remain unknown." (PMID 34784362, 2021). "Furthermore, upon infection the bronchoalveolar and thoracic cavity lavage of S100A8/A9-/- mice showed increased concentrations of CXCL-1, CXCL-2, CXCL-5, as well as elastase in comparison to the WT controls." (PMID 32107497, 2020). "We also observed keratinocytes at the site of infection expressing S100A8/A9 complex." (PMID 33031460, 2020).